IGKV1D-33 (immunoglobulin kappa variable 1D-33)
Description:
V region of the variable domain of immunoglobulin light chains that participates in the antigen recognition. Immunoglobulins, also known as antibodies, are membrane-bound or secreted glycoproteins produced by B lymphocytes. In the recognition phase of humoral immunity, the membrane-bound immunoglobulins serve as receptors which, upon binding of a specific antigen, trigger the clonal expansion and differentiation of B lymphocytes into immunoglobulins-secreting plasma cells. Secreted immunoglobulins mediate the effector phase of humoral immunity, which results in the elimination of bound antigens. The antigen binding site is formed by the variable domain of one heavy chain, together with that of its associated light chain. Thus, each immunoglobulin has two antigen binding sites with remarkable affinity for a particular antigen. The variable domains are assembled by a process called V-(D)-J rearrangement and can then be subjected to somatic hypermutations which, after exposure to antigen and selection, allow affinity maturation for a particular antigen.
Synonyms: IGKV1D33; O8
Tractability: Antibody: its Gene Ontology location is reachable by antibodies, with high confidence; UniProt places it where antibodies can reach, with medium confidence; UniProt predicts a signal peptide or a membrane-spanning region.
Gene: Immunoglobulin variable (V) gene on chromosome 2 (89,913,982 to 89,914,545, forward strand). Ensembl gene ENSG00000239975.
Subcellular location: Secreted; Cell membrane
Pathways (Reactome):
Immune System: Antigen activates B Cell Receptor (BCR) leading to generation of second messengers; CD22 mediated BCR regulation; Classical antibody-mediated complement activation; FCERI mediated Ca+2 mobilization; FCERI mediated MAPK activation; FCERI mediated NF-kB activation; FCGR activation; Fc epsilon receptor (FCERI) signaling; Immunoregulatory interactions between a Lymphoid and a non-Lymphoid cell; Initial triggering of complement; Regulation of Complement cascade; Regulation of actin dynamics for phagocytic cup formation; Role of LAT2/NTAL/LAB on calcium mobilization; Role of phospholipids in phagocytosis
Disease: FCGR3A-mediated IL10 synthesis; FCGR3A-mediated phagocytosis; Potential therapeutics for SARS
Hemostasis: Cell surface interactions at the vascular wall
Vesicle-mediated transport: Scavenging of heme from plasma
Gene Ontology:
Molecular function: antigen binding
Biological process: immune response
Cellular component: blood microparticle; extracellular exosome; extracellular region; immunoglobulin complex; plasma membrane
Homologues: Paralogues in human: IGKV1-33 (100% identical), IGKV1-39 (88% identical), IGKV1D-39 (88% identical), IGKV1D-13 (86% identical), IGKV1-27 (85% identical), IGKV1-6 (85% identical), IGKV1-9 (85% identical), IGKV1-12 (84% identical), IGKV1-16 (84% identical), IGKV1-37 (84% identical), IGKV1-5 (84% identical), IGKV1D-37 (84% identical), and 81 more.